CCL25 (C-C motif chemokine ligand 25)
Diseases named in the same sentence as CCL25 in open-access papers (continued):
Sharing a sentence is not in itself a finding about the gene and the disease.
COVID-19 (13 papers, 2020 to 2025). A disease caused by infection with severe acute respiratory syndrome coronavirus 2. "Although we found a strong and significant positive relationship between blood glucose and CCL25 levels, linking this causatively to glucose homeostasis in COVID-19 requires further investigation." (PMID 39164284, 2024). "Interestingly, the longitudinal data from COVID-19 patients also showed that a clinical improvement is often associated with increased CCL25 concentration." (PMID 35634344, 2022). "After adjustment for confounding factors, seven proteins that were highly abundant and associated with an increased hazard of critical COVID-19 outcome were SLAMF1, CCL25, IL2RB, IL10RA, IL15RA, IL18 and CST5." (PMID 40475767, 2025). "Multiple studies show high levels of proinflammatory cytokines such as IL-1, TNF, IFNs, IL-6, IL-8, IL-18, IL-17α, G-CSF, and GM-CSF, as well as chemokines, such as MCP-1, IP-10, MIP-1α, CXCL10, CCL2, CCL4, CCL14, CCL19, and CCL25 in severe cases of COVID-19." (PMID 40076291, 2025). "Here, we demonstrated that the unique signature featuring SLAMF1, CCL25, IL2-RB, IL10RA, IL15RA, IL18, and CST significantly increased the risk of critical illness in COVID-19 patients." (PMID 40475767, 2025). "A decreased abundance of a cluster of several leukocyte chemotactic factors (MCP-4, CXCL12, CCL11, CCL19, CCL25, and CCL20) was observed in the COVID-19 cases and associated with a decrease in the cytotoxic T-cell marker CD8A." (PMID 34710339, 2022). "Interestingly, autoantibodies against CCL25 are augmented in mild COVID-19 patients compared to those requiring hospitalization." (PMID 39164284, 2024). "The combination of antibody values against CXCL5, CXCL8 and CCL25 at month 6 alone could correctly assign formerly hospitalized and outpatient COVID-19 convalescents with an accuracy of 77.5% (‘COVID-19 hospitalization signature’)." (PMID 36879067, 2023). "Compared with the controls, LBP and CCL25 were significantly increased in COVID-19 patients." (PMID 33139693, 2020). "Thus, the chemokine antibody signature that distinguished healthy controls from COVID-19 convalescents (autoantibodies to CCL19, CCL22 and CXCL17) was different from the signature associated with COVID-19 severity (autoantibodies to CXCL5, CXCL8 and CCL25)." (PMID 36879067, 2023). "Subgroup analyses of the five deceased COVID-19 patients (all males) revealed significantly upregulated proteins such as CD8A, SLAMF1 and LIF-R, HGF, CCL25, NT3 compared to the surviving patients." (PMID 37832397, 2023). "Of note, CXCL5, CXCL8 and CCL25, which correspond to the chemokine antibodies representing the COVID-19 hospitalization signature, were not significantly different between mild and severe hospitalized COVID-19 convalescents in the Milan cohort." (PMID 36879067, 2023). "Antibodies against CXCL5, CXCL8 and CCL25 were all lower in previously hospitalized compared with outpatient COVID-19 convalescents, and this was not linked to the therapy received during hospitalization." (PMID 36879067, 2023). "Higher levels of several of these proteins were inversely correlated with viral load, including the cytosolic RNA sensor RIG-I (gene symbol DDX58), chemokines (CCL20 and CCL25), and other proteins (Keratin 19 [KRT19], amphiregulin [AREG]) previously shown to be upregulated in COVID-19 patients." (PMID 36239699, 2022). "Levels of SLAMF1, CCL25, IL2RB, IL10RA, IL15RA, IL18 and CST5 were significantly upregulated in patients with critical COVID-19 illness compared to individuals negative for COVID-19." (PMID 40475767, 2025).
melanoma (13 papers, 2013 to 2025). A malignant, usually aggressive tumor composed of atypical, neoplastic melanocytes. "We analyzed variations of CCL25 expression in tumor samples from patients with melanoma treated with anti–PD-1 and showed that sustained CCL25 expression during ICB characterized patients responding versus nonresponding to the therapy." (PMID 41042869, 2025). "A good example is the CCR9-mediated metastasis of a subset of melanoma cells to the intestine due to the expression of CCL25 there, which is intriguing considering the normal role of CCR9:CCL25 in the recruitment of CCR9+ T cells via activation of α4β7." (PMID 37173970, 2023). "Studies have shown that CCR9 is highly expressed in melanoma skin lesions, and that melanoma cells are specifically targeted to the small intestine when CCL25/CCR9 signaling is activated." (PMID 26879872, 2016). "As migration of CCR9-postive lymphocytes to the small intestine relies on chemoattractive effects of CCL25 and the action of αβ integrin heterodimers, studies suggest CCR9-CCL25 also mediates melanoma metastasis to the small intestine." (PMID 24259307, 2013). "Similarly, the neutralization of CCL25 also promoted tumor growth in a CCL25-expressing mouse melanoma model." (PMID 34771505, 2021). "The immunohistochemical images of IFNGR2, CCL25, IL15, RTP4, and NLRP6 in both normal skin tissue and melanoma tissue confirmed the expression of the GRIPs in CM." (PMID 35492358, 2022). "This may be related to the high expression of C-C motif chemokine ligand 25 (CCL25), a ligand for the C-C chemokine receptor type 9 (CCR9), in the small intestine, which may facilitate migration of melanoma cells from the skin to the small bowel." (PMID 41311777, 2025). "Notably, the combined expression of CCR9, CCL25, CD8A, and CD8B genes in tumors positively correlated with a higher DSS probability in patients with melanoma, with a better hazard ratio (HR) and P value compared to the expression of CD8A and CD8B genes only." (PMID 41042869, 2025).
inflammatory bowel disease (11 papers, 2015 to 2025). A spectrum of small and large bowel inflammatory diseases of unknown etiology. "The expression of CCR9 on monocytes and the CCR9/CCL25 axis have been associated with autoimmune diseases such as inflammatory bowel disease, rheumatoid arthritis (RA), and ankylosing spondylitis." (PMID 38247848, 2024). "The interaction of CCL25 and its receptor is involved in T cell development and gut-associated immune responses, as well as participating in various inflammatory diseases and contributing to inflammatory responses, including inflammatory bowel disease." (PMID 37587523, 2023). "Significant upregulation of CCR9, CCL25, and MAdCAM-1 suggests increased lymphocyte trafficking to the gut, similar to mechanisms described in human inflammatory bowel disease." (PMID 40564263, 2025). "In recent years, research has brought more evidence of how CCR9/CCL25 contributes to inflammation, which are associated with several diseases, including cardiovascular disease (CVD), hepatitis, arthritis, inflammatory bowel disease, and asthma." (PMID 39199524, 2024). "Serum levels of CCL25 along with other chemokines and cytokines are increased in patients with inflammatory bowel disease." (PMID 33224151, 2020). "In the context of CCR9-dependent pDC distribution in mice, we successfully confirmed the upregulation of CCL25 in human small intestines from patients with Crohn’s disease, which is consistent with a previous report on the abundance of gut-tropic pDCs in patients with inflammatory bowel disease." (PMID 35943802, 2022). "Modulation of the interaction between CCL25 and its receptor CCR9 is recognized as a therapeutic strategy against the mucosal inflammation in patients with Crohn’s disease, and in inflammatory bowel disease." (PMID 33224151, 2020). "Due to the upregulation of CCL25 and recruitment of CCR9+ immune cells in the gut of inflammatory bowel disease (IBD) patients, CCR9 is considered as a potential therapeutic target to control gut inflammation." (PMID 33123124, 2020). "Over the years, the role of CCR9/CCL25 in inflammation and related diseases has become increasingly clearness, including cardiovascular disease (CVD), hepatitis, arthritis, inflammatory bowel disease, and asthma." (PMID 34490243, 2021). "The principal targets for anti-chemokine therapy in inflammatory bowel disease (IBD) have been the receptors CCR9 and CXCR3 and their respective ligands CCL25 and CXCL10." (PMID 30137309, 2018). "In colon from inflammatory bowel disease (IBD) patients with active colonic inflammation, CCL25 mRNA was detected by one group but not by two others." (PMID 26457007, 2015).
ovarian carcinoma (9 papers, 2014 to 2022). A malignant neoplasm originating from the surface ovarian epithelium. "Reference 98 to “Singh, R.; Stockard, C.R.; Grizzle, W.E.; Lillard, J.W., Jr.; Singh, S., Expression and histopathological correlation of CCR9 and CCL25 in ovarian cancer." (PMID 31146450, 2019). "The correct reference is “Singh, R.; Stockard, C.R.; Grizzle, W.E.; Lillard, J.W., Jr.; Singh, S., Expression and histopathological correlation of CCR9 and CCL25 in ovarian cancer." (PMID 31146450, 2019). "Specific examples include CCL5 and CCL25 and their cognate receptors CCR5 and CCR9 in breast and ovarian cancers, respectively." (PMID 29358632, 2018). "Studies have found that the interaction of CCL25/CCR9 can increase the expression of MMP-2 and MMP-9, which induce tumor metastasis in a variety of cancers, such as ovarian cancer, prostate cancer, non-small cell lung cancer, and endometriosis." (PMID 26879872, 2016). "Recent studies have shown that CCL25/CCR9, via activating the PI3K/AKT signaling pathway, mediated anti-apoptotic processes in lung cancer, induced etoposide resistance in prostate cancer, and induced cis-platinum resistance, which is dependent on PI3K and not FAK, in breast and ovarian cancer." (PMID 26879872, 2016).
Crohn disease (8 papers, 2010 to 2022). A gastrointestinal disorder characterized by chronic inflammation involving all layers of the intestinal wall, noncaseating granulomas affecting the intestinal wall and regional lymph nodes, and transmural fibrosis. "In Crohn's disease altered expression of GM-CSF and CCL25 has been suggested to play a role in the pathogenesis of inflammatory gastrointestinal disease." (PMID 28018296, 2016). "The levels of colonic CCL25 had been shown to increase in both Crohn’s disease and ulcerative colitis, and pharmacological inhibitors of CCR9 prevented the development of ulcerative colitis in an experimental model." (PMID 27832135, 2016). "Colon biopsies obtained from patients with active Crohn's disease (CDAI ≥ 250) had significantly higher levels of CCL25 protein than healthy colon samples." (PMID 26457007, 2015). "Levels of CCL25 protein were measured in colon tissue from healthy individuals and Crohn's disease and ulcerative colitis patients, as well as Crohn's disease terminal ileum." (PMID 26457007, 2015). "CCL25 levels were also significantly higher in colon biopsies from individuals with active Crohn's disease (CDAI ≥ 250)." (PMID 26457007, 2015). "In inflamed small intestine in Crohn's disease CCL25 expression is in epithelial cells in proximity to lymphocytic infiltrates and is not detectable on endothelial cells." (PMID 20738854, 2010). "However, contradicting results have emerged in the role of CCL25/CCR9 interactions in the experimental small intestinal inflammation of the TNFΔare mouse model that mimics human Crohn's Disease." (PMID 21283540, 2011). "The increase in colonic CCL25 levels was not restricted to Crohn's disease, since colon biopsies from ulcerative colitis patients also contained significantly elevated levels of CCL25 protein." (PMID 26457007, 2015). "Interestingly, CCL25 levels in the terminal ileum of Crohn's disease patients were not higher than the levels of CCL25 in the colon of these patients or ulcerative colitis patients." (PMID 26457007, 2015). "The fact that these studies were focused on small intestinal but not large intestinal inflammation, made CCL25 and CCR9 attractive candidates for the treatment of Crohn's disease but not ulcerative colitis." (PMID 21283540, 2011).
ulcerative colitis (8 papers, 2011 to 2025). An inflammatory bowel disease involving the mucosal surface of the large intestine and rectum. "Under local inflammatory conditions, expression of CCL25 in the colon can be induced as observed in patients with ulcerative colitis (UC) where it correlated with disease severity." (PMID 35598439, 2022). "Colon samples from patients with ulcerative colitis had significantly higher levels of CCL25 protein compared to healthy controls, a finding mirrored in the mdr1a−/− mice." (PMID 26457007, 2015). "Toward this end, we compared colonic CCL25 protein levels in healthy individuals to those in patients with ulcerative colitis." (PMID 26457007, 2015). "Then we show that the levels of colonic CCL25 protein are elevated, compared to healthy controls, both in patients with ulcerative colitis and in the mdr1a−/− mouse model of ulcerative colitis." (PMID 26457007, 2015). "CCL25 levels in colon biopsies from individuals with ulcerative colitis were significantly higher than CCL25 levels in normal colon." (PMID 26457007, 2015). "Intriguingly, the mRNA and protein products of these REG genes and CCL25 gene were highly expressed in autoimmune/inflammatory diseases of the intestinal tract including ulcerative colitis (UC), a condition with a high probability of development of colon cancer." (PMID 29088818, 2017). "In the mdr1a−/− mouse model of ulcerative colitis, increased colonic CCL25 protein levels were noted before any clinical manifestations of disease and correlated temporally with increases in the frequency of circulating CCR9+CD4+ T cells, which we used as a surrogate for intestinal inflammation." (PMID 26457007, 2015). "This suggests that blocking CCL25/CCR9 interactions in ulcerative colitis patients may lead to an inefficiency in resolving intestinal inflammation or, at worst case, even exacerbated IBD symptoms." (PMID 21283540, 2011). "However, in mice and healthy humans CCL25 expression is restricted to the small bowel, whereas few data exist on activation of this pathway in the inflamed colon despite the vast majority of PSC patients having ulcerative colitis." (PMID 26873648, 2016). "As CCL25/CCR9 interactions are currently considered dispensable for the regulation of inflammation in the large intestine, the therapeutic effect of the CCR9-antagonist has not been studied in ulcerative colitis." (PMID 21283540, 2011).
lung carcinoma (7 papers, 2015 to 2025). "Gupta further revealed that lung adenocarcinoma cells produce TIMP-1 and TIMP-2, whereas lung SCC cells only express TIMP-2, suggesting that MMP and TIMP differential expression, mediated by the CCR9/CCL25 axis, influences lung cancer metastasis and invasion." (PMID 40607416, 2025). "Gupta reported that MMP-2 promotes CCR9/CCL25 interactions, facilitating lung cancer cell invasion and selective metastasis." (PMID 40607416, 2025). "The CCR9/CCL25 axis could promote the proliferation of lung cancer cells by inhibiting the apoptosis of tumor cells." (PMID 36003306, 2022). "Chemokines, particularly the CCR9/CCL25 and CXCL12/CXCR4 axes, play pivotal roles in lung cancer progression, immune cell recruitment, and tumor microenvironment remodeling." (PMID 40607416, 2025). "This review systematically summarizes the biological functions and molecular mechanisms of the CCR9/CCL25 and CXCL12/CXCR4 axes in lung cancer." (PMID 40607416, 2025). "In lung cancer, the CCL25/CCR9 axis promotes cancer progression, but intratumoral delivery of CCL25 attracts CCR9+ CD8+ T cells to infiltrate the tumor and enhances CD47-targeted immunotherapy in a murine TNBC model." (PMID 34771505, 2021). "Interestingly, additional Transwell experiments showed that CCR9/CCL25 promoted the migration and invasiveness of lung cancer stem cells isolated from A549 cells, and the authors suggested that CCR9 or its ligand CCL25 could be used as a therapeutic target for lung adenocarcinoma." (PMID 35740564, 2022).
prostate carcinoma (6 papers, 2010 to 2022). A carcinoma that arises from epithelial cells of the prostate gland. "We have previously shown that CCR9 and CCL25 play significant role in prostate cancer cell survival, which is required for cancer cells to achieve their metastatic goal." (PMID 25296976, 2014). "We have previously shown that CXCL12 and CCL25 can modulate the expression of MMPs by prostate cancer cells." (PMID 20649989, 2010). "Interestingly, in prostate cancer cells, no MMP8 was detected even after induction with CCL25." (PMID 31514474, 2019).
asthma (5 papers, 2016 to 2025). "The CCR9/CCL25 axis functions in homeostasis, inflammation, and inflammation-associated diseases including early respiratory allergic inflammation, asthma, chronic inflammatory bowel diseases, and organ fibrosis." (PMID 35862771, 2022). "Furthermore, the study holds significant translational potential: serum CCL25 levels may serve as a predictive biomarker for asthma recurrence." (PMID 40861437, 2025). "CCR9/CCL25 is participated in many inflammatory diseases, including CVD, hepatitis, RA, IBD, and asthma." (PMID 34490243, 2021). "CCR9/CCL25 signal can interact with CD226 signaling to activate asthmatic NKT cells, leading to airway hyperresponsiveness and inflammation, aggravating asthma." (PMID 34490243, 2021).
hepatocellular carcinoma (5 papers, 2020 to 2025). A malignant tumor that arises from hepatocytes. "Chronic hypoxia does not affect CCL25/thymus-expressed chemokine (TECK) expression, as shown in lung adenocarcinoma cells and hepatocellular carcinoma cells." (PMID 32781743, 2020).
lung adenocarcinoma (5 papers, 2015 to 2025). A carcinoma that arises from the lung and is characterized by the presence of malignant glandular epithelial cells. "MMP-2 exhibits greater reactivity to CCL25 in lung adenocarcinoma compared to lung SCC, likely due to differential MMP activity and CCR9 phosphorylation." (PMID 40607416, 2025). "The expression of CCR9 and its ligand CCL25 in the tumor tissues of lung adenocarcinoma patients was investigated using immunohistochemistry." (PMID 32308544, 2020). "The expression and activity of MMP-2 in response to CCL25 were greater in lung adenocarcinoma cells compared with squamous cell carcinoma cells." (PMID 26168791, 2015). "Our findings provided evidence that CCR9/CCL25 could be used as novel therapeutic targets for lung adenocarcinoma." (PMID 32308544, 2020). "Furthermore, the number of lung adenocarcinoma cells that migrated and invaded in response to CCL25 is greater compared with lung squamous cell carcinoma cells." (PMID 26168791, 2015). "However, the expression of CCL25 was barely detect in lung adenocarcinoma tissues." (PMID 32308544, 2020).
pancreatic cancer (5 papers, 2016 to 2025). "In a tumor, CCL25 is produced by cancer cells, such as breast cancer cells and pancreatic cancer cells, and also by cancer-related cells, e.g., pancreatic stellate cells in pancreatic cancer." (PMID 33076281, 2020). "The CCL25/CCR9 axis reportedly enhances cell proliferation, invasion, and drug resistance via β-catenin activation in pancreatic cancer cells, suggesting that β-catenin signaling may also be involved in T-ALL cell migration and invasion." (PMID 28380463, 2017). "Most cancer cells upregulate CCR9 to mediate metastasis, and some cancers secrete CCL25 in a paracrine fashion; these cells include pancreatic cancer PSCs and PANC-1 cells, which then induce metastasis by binding the secreted CCL25 to CCR9 receptors in the nearby tissues." (PMID 26879872, 2016).